ENSG00000212187
Synonyms: LOC124900448
Gene: Small nucleolar RNA gene on chromosome 1 (212,025,561 to 212,025,682, forward strand). Ensembl gene ENSG00000212187.
Gene Ontology:
Biological process: RNA processing
Cellular component: nucleolus
Homologues: Orthologues: rat LOC120102083 (80% identical), rat LOC120095458 (61% identical), rat LOC120099029 (61% identical). Paralogues in human: SNORA26 (89% identical).